RAC1 (Rac family small GTPase 1)
Diseases named in the same sentence as RAC1 in open-access papers (continued):
Sharing a sentence is not in itself a finding about the gene and the disease.
cancer (continued). "CEFs induced cancer cell spreading via IL‐1β secretion, which activates Rac1 in cancer cells." (PMID 34379869, 2022). "To elucidate whether CSDE1 regulates cancer malignancy by regulating Rac1 expression, we rescued Rac1 expression in CSDE1-knockdown cells." (PMID 35490208, 2022). "For vinorelbine, EPHA2 codes for EPH receptor A2, a tyrosine kinase involved in cancer-related signaling, while NGEF codes for a guanine nucleotide exchange factor associated with signaling from EPH receptor A2, RhoA, Rac1 and CDC42 as well as cellular transformation and tumorigenesis." (PMID 36139690, 2022). "SH3BP1 has been shown to activate Rac1 to regulate cancer cell behavior." (PMID 35352878, 2022). "Pan-cancer data showed that Rac1 was upregulated in 374 HCC patients." (PMID 35847360, 2022). "A gene expression analysis of cancer cells exposed to that treatment identified Myc and Rac1, one of the critical factors in the maintenance of the intestinal barrier and upregulated in primary and metastatic CRCs, as major candidates driving acquired resistance." (PMID 35158939, 2022). "Thus, the detection of activated Rac1 in cancer tissues enables the prediction of the invasive property of tumor cells, forthcoming metastasis, and patient prognosis, thereby making it a useful biomarker." (PMID 35110666, 2022). "Thus, our study indicated a novel therapeutic strategy for RAC1 overactivated cancers by modulation of MG53." (PMID 35858925, 2022). "p66Shc appears to activate mTOR, Akt, ERK, and Rac1, and regulate the activation of migration-related proteins through ROS (reactive oxygen species) in cancer cells, thus it may be involved in cancer cell development and progression." (PMID 35886904, 2022). "RAC1 activity is recognized to play a pivotal role in cancer including HCC, thus it is plausible that MG53-induced negative regulation of RAC1 might be critically involved in the progression of HCC." (PMID 35858925, 2022). "Therefore, inhibiting the expression and activation of RAC1 is critical for the suppression of cancer progression." (PMID 35858925, 2022). "It has been reported that RhoA and Rac1 signaling pathways promote EMT in malignant tumors." (PMID 35075114, 2022). "The intrinsic GDP/GTP exchange activities of Rac1 are critical for mobilization of the actin filament system, leading to lamellipodia formation at the leading edge of migratory cells, including tissue invading cancer cells." (PMID 35327364, 2022). "Western blot analysis of tumor tissue lysates revealed that TBOPP treatment obviously suppressed the metformin-induced RAC1 activation, which confirmed that RAC1 activation contributes to the DOCK1 suppression associated sensitization of cancer cells to metformin in vivo." (PMID 35217990, 2022). "PTK2 activates Rac1 to promote invasive properties in carcinoma cells." (PMID 35456223, 2022). "Contrary to recent studies that report the identification of new driver mutations in some RHO GTPases members, such as RAC1, RHOA, and CDC42, analysis of cancer genomes has demonstrated that mutations affecting RHO signaling pathways are found at low frequency in a limited spectrum of tumor types." (PMID 34771549, 2021). "We next used the KTC1 and PDX.008.CL cell lines, as well as the metastatic patient sample to quantify copy number and expression of several cancer-related genes located on chromosome 7p and 7q, including RAC1 (7p22.1) TWIST1 (7p21.1), EGFR1 (7p11.2), MET (7q31.2) and BRAF (7q.34)." (PMID 34638434, 2021). "It has been found that Rac1 is highly expressed and over-activated in many cancers." (PMID 34079763, 2021). "Moreover, the RAC1 signaling pathway plays a central role in angiogenesis, cancer metastasis, tumor development, chemoresistances and invasion." (PMID 34803511, 2021). "Thus, RAC1 signaling pathway is considered an important and potential therapeutic target in different types of cancer." (PMID 34803511, 2021).
cancer (continued). "Hence, any disturbances in each step of regulation produce critical changes to the expression and activity of RAC1, which in many cases can lead to cancer progression and metastasis." (PMID 34771549, 2021). "Hypoxia enhances RAC1 activity in cancer cells, which in turn is required for HIF1 accumulation." (PMID 34827551, 2021). "Considering that RAC1 and RAC1b control TGFβ responses in cancer cells in an antagonistic manner, the final outcome of TGFβ signal transduction, in a given tissue or cell type, appears to be strictly dependent on RAC1b/RAC1 ratio." (PMID 33672325, 2021). "Consistently, stable co-knockdown of RAC1 in HACE1 deficient cells inhibits HIF1α accumulation in these cells, suggesting targeting of RAC1 is a potential mechanistic intervention point for targeted therapy in diverse cancer types." (PMID 33603169, 2021). "While RAC1 plays an essential role in mouse embryogenesis, genome-wide screens have found that RAC1 could be knocked out in cells from several cancer types." (PMID 34373577, 2021). "The exact mechanism for this cancer development is still not well understood, but it might be due to the ability of RhoH to regulate the activities of other cancer-related small Rho GTPases, including RhoA, Cdc42, Rac1 and RhoF." (PMID 33923951, 2021). "Conversely, in cells expressing E7 mutant isoforms, increased RhoA GTP could repress Rac1 activity, promoting an amoeboid-like movement of cancer cells." (PMID 33477952, 2021). "The Rho family of GTPases, e.g., Rac1, and the associated kinases, e.g., ROCK, are involved in key oncogenic signaling pathways, particularly by activating the actomyosin network and promoting cancer invasion and metastasis." (PMID 34325694, 2021). "We find that the Golgi apparatus pathways predominate over the Rac1/Cdc42 signaling pathways in controlling the cancer cell polarization, in contrast to the polarization of healthy tissues and cells that are primarily controlled by the Rac1/Cdc42 signaling pathways." (PMID 33499191, 2021). "Unbalanced expression or activation patterns of Rac1 may lead to abnormal cell signal transduction and diseases, such as cancer." (PMID 34079763, 2021). "Since Rac1 is often overexpressed and/or overactivated in cancers, the hypothesis that lipin-1 may be involved in tumor biology was raised." (PMID 33922580, 2021). "DEPDC1B could regulate RAC1 activity by increasing GTP loading in RAC1 instead of affecting Rho A activities in normal or cancer cells." (PMID 35095994, 2021). "Considering PAK2 key role in cardiac function, its clinical application is questionable; nevertheless, PAK1 inhibitors might be refined for RAC1-driven cancer treatment." (PMID 34827551, 2021). "Rho-family GTPases have Cdc42, Rac1, and RhoA as the main subfamily and play important roles in various cell functions including angiogenesis and invasion, cytoskeletal structure formation, cell proliferation, apoptosis, and cancer metastasis." (PMID 34201921, 2021). "It is hypothesized that mesenchymal component of the mixed tumors in dogs arise from myoepithelial cells, while RAC1 is indicated in promotion of epithelial–mesenchymal transition in various human cancers." (PMID 34679042, 2021). "BRD4 and RAC1 oncoproteins play important roles in cancer cell growth, migration, invasion and metastasis, hence the focus on these two oncogenes as potential therapeutic targets in different cancers 23,50,51." (PMID 34803511, 2021). "A meta-analysis shows that high expression of Rac1 could predict the poor prognosis of cancer patients." (PMID 34079763, 2021).
cancer (continued). "Therefore, abnormal expression of Rac1 can be used as a monitoring index for the progression and poor prognosis of different types of cancers." (PMID 34079763, 2021). "Given the ability of the natural phytoalexin resveratrol to reduce the risk of OSCC as well as other cancers, we wondered whether this compound may interact with the endogenous tumor-suppressing activity of ZNF750/RAC1 signaling pathway in OSCC cells." (PMID 34176441, 2021). "RAC1 enhances cancer stemness and self-renewal capacity in HCC." (PMID 34621787, 2021). "Interestingly, overexpression of wild-type RAC1 has been observed in many cancers and correlates with poor prognosis as well as resistance to chemotherapy." (PMID 34638434, 2021). "In this context, ARHGAP22 protein has been previously shown to specifically inhibit RAC1 activity thus standing as critical cytoskeleton regulator in cancer cell models; however, whether this function is maintained in neurons in the CNS is unknown." (PMID 34455539, 2021). "Accordingly, the LCAT1-miR-4715-5p-RAC1/PAK1 axis could be a specific target for the treatment of lung cancer patients with LCAT1 overexpression in their cancer cells." (PMID 34771549, 2021). "R-ketorolac may hold promise for future clinical use in cancers with elevated Rac1 and/or Cdc42 expression or activity." (PMID 33413202, 2021). "Treatment of endometrial cancer (Ishikawa cells) with Uro-A (20 μM) significantly decreased the activity and mRNA levels of Rac1 and PAK1, and this resulted in actin depolymerization, which is associated with a decreased cancer cell proliferation and migration." (PMID 34164422, 2021). "The expression of Rac1 regulates the sensitivity of cancer to chemotherapy." (PMID 34079763, 2021). "In addition, ΔNp63α inhibited the PKCγ/Rac1 signaling pathway by positively regulating miR-320a, thereby inhibiting cancer invasion." (PMID 34930262, 2021). "We found that GRB2 and RAC1 gene expression levels were increased in the III grade carcinomas." (PMID 34679042, 2021). "Accumulating evidence indicates that Rac1 is overexpressed and hyperactivated in a wide range of tumors and its influence on cytoskeleton remodeling affects key processes such as invasion, migration, and metastasis of cancer cells." (PMID 32351958, 2020). "We sought to further investigate whether Rac1 inactivation was responsible for inhibition of cancer cell invasion by suppressing NF-κB-mediated MMP-2/-9 expression, by transient ectopic expression of NF-κB p65 in cells in the presence of GA or NSC23766." (PMID 32823607, 2020). "Rac1 and Cdc42 are unique in that they act as molecular switches that do not have to be mutated to drive cancer progression but are activated by oncogenic cell surface receptors." (PMID 32322580, 2020). "Furthermore, TGF‐β secreted by cancer cells activates a RAC1/SMAD‐mediated signaling pathway in mesothelial cells, which results in transcriptional upregulation of the fibronectin gene and induces an EMT‐like phenotype in mesothelial cells." (PMID 32963283, 2020). "Although the mechanism of this mutation on tumorigenesis is unclear, since RhoA signaling is inversely correlated with Rac1 in some cancers, one possibility is that reduced RhoA activity may promote tumorigenesis through enhanced Rac1 signaling." (PMID 32392742, 2020). "This may be due to the fact that coordinated events between Rac1 and RhoA are necessary for effective migration in cancer metastasis." (PMID 32722576, 2020). "Interestingly, Ehop-016, a Rac1 and Rac3 inhibitor, significantly reduced Ser2P and Ser5P levels in both cancer cell lines, although it also slightly reduced Ser7P in HeLa cells." (PMID 32143485, 2020). "Similarly, the effect of anti-cancer phytochemical rocaglamide-A inhibited the activity of RhoA, Rac1, and Cdc42 GTPases and suppressed metastasis formation." (PMID 32443784, 2020). "The dysregulation of Rac1 activation has been reported in multiple diseases, including cancer." (PMID 32092966, 2020).
cancer (continued). "Furthermore, Rac1 has been shown to have additional functions that contribute to cancer progression, including ROS formation, proliferation, gene expression and ribosomal biogenesis." (PMID 32092966, 2020). "Intriguingly, both RAC1 activity and CDC42 activity have been associated with therapeutic resistance in different cancer types, including enzalutamide resistance in CRPC, and RAC/CDC42 inhibition has been suggested as a potential approach to overcome resistance to PI3K–AKT–mTOR-targeted treatments." (PMID 33105713, 2020). "RAB5B regulates cell adhesion and migration by promoting Rac1 activation and cancer cell migration." (PMID 33154765, 2020). "Herein, we applied siRNA to target Rac1 mRNA instead of its protein for cancer treatment." (PMID 32193458, 2020). "Rac1 has previously been shown to be involved in the defective activation of several signaling cascades leading to anomalous behavior of cells and ultimately contributing to cancer progression." (PMID 32351958, 2020). "Therefore, blocking the Tiam1/Rac1 interaction has the potential to reduce metastasis from multiple cancer types." (PMID 32322580, 2020). "Clearly, these essential cellular functions mediated by Rac1 could be exploited in pathological conditions such as cancer, whereby cells rely on Rac1 to invade surrounding tissues." (PMID 33302361, 2020). "As a result, rac1, the primary mediator for endocytosis, becomes essential for cancer cell metabolism and could be a valuable drug target." (PMID 32224866, 2020). "Its metastasis-promoting function might be also activated by the small GTPases, Rac-1 and Rab-5 in cancer cells." (PMID 33381039, 2020). "Rac1 is overexpressed in various cancers such as testicular cancer, breast cancer, and leukemia." (PMID 32802134, 2020). "Indeed, a number of NSCLC cancer cells growing in culture display elevated basal levels of Rac1-GTP, providing strong evidence for Rac1 signaling hyperactivation." (PMID 32158759, 2020). "RAC1-driven cancer cell invasion involves both single-cell and collective modes of migration." (PMID 33266416, 2020). "In addition, some DGKs control cancer cell migration by regulating the activities of the Rho GTPases Rac1 and RhoA." (PMID 32722576, 2020). "PKC-ζ has been shown to be involved in tumorigenesis, tissue invasion, and cancer progression through the modulation of cell migration machinery, such as Ras Homolog Family Member A (RhoA), Rac Family Small GTPase 1 (Rac1), and Epithelial Cell Transforming 2 (Ect2)." (PMID 32175276, 2020). "This study provides valuable insights for the cancer treatment based on the inhibition of Rac1." (PMID 33604328, 2020). "Understandably, none of the RAC1-mediated cell signaling relevant to the development of resistance in different cancers has been associated with a direct alteration of the genome." (PMID 32545340, 2020). "They observed that RAC1 inhibition led to the decreased expression of several glycolytic enzymes which are present in aerobic glycolysis and are believed to promote the resistance of cancer cells to chemotherapies." (PMID 32545340, 2020). "Based on the gene expression analysis, FD extract had reduced the expression of the TWIST1 and RAC1 genes associated with epithelial-mesenchymal transition (EMT) and had significantly downregulated the COX-2 and EGFR genes associated with cancer angiogenesis, metastasis, and chemoresistance." (PMID 32104177, 2020). "Therefore, there is an urgent need to develop an effective combination therapy of RAC1 inhibitor and paclitaxel for this subgroup of cancer patients." (PMID 31779616, 2019). "Upon the activation of Rac1 and RhoA, cancer cells migration are enlarged." (PMID 31870092, 2019). "Furthermore, RAC1 signaling provides a novel insight into the mechanisms of cancer cell survival under ER stress (endoplasmic reticulum stress)." (PMID 31027363, 2019). "In addition, one of the approaches that RAC1 uses to control cancer cell metabolism is by interacting with mTOR." (PMID 31314174, 2019).
cancer (continued). "In particular, Rac1 is involved in several phases of cancer development, as it can promote cancer initiation, cancer progression, and metastases through its role in gene transcription, cell cycle progression, neovascularization, cell adhesion, migration, and invasion." (PMID 31035701, 2019). "In summary, disrupting the regulation of Rac1 signaling and actin dynamics may drive the invasiveness and spread of various cancers and the role of CYRI in this process warrants further study." (PMID 31413787, 2019). "Together these results show that by inhibiting pro-apoptotic Rac1, α2β1 integrin can be a major pathway protecting leukemic cells from genotoxic agents and may thus represent an important therapeutic target in anti-cancer treatment." (PMID 31857649, 2019). "Besides, co-treatment of miR-139/LPN-HR and Afa/LPN-HR also significantly reduced the protein expression of Rac1 and KRAS and the associated phospho-Erk, phospho-MAPK, and COX-2, thereby notably weakening cancer cell growth and progression." (PMID 31426807, 2019). "This study was the first to discover that azathioprine-RAC1 gains associations in ESCC, which could help to expand the research of azathioprine in the anti-cancer field." (PMID 31700061, 2019). "Furthermore, deregulation of certain Arf family members, such as Arf1 and Arf6, enhances cancer cell invasion and metastasis by stimulating Ras-related C3 botulinum toxin substrate 1 (Rac1), paxillin, talin or focal adhesion kinase (FAK)." (PMID 30884855, 2019). "Additionally, a recent study showed that gonadotropin-releasing hormone regulates p120ctn cytoplasmic translocation to promote cancer cell migration and invasion via Rac1 and Cdc42." (PMID 30795761, 2019). "Increased GDP→GTP nucleotide exchange by RAC1-GEF in the context of the event of the activation of RAC1 mediates oncogenic effects, while alterations in RAC1-GAPs are not generally cancer associated." (PMID 31027363, 2019). "RAC1 hyper activation is common in human cancers and could be the consequence of overexpression, abnormal upstream inputs, deregulated degradation, and/or anomalous intracellular localization." (PMID 31027363, 2019). "We also discuss how simultaneous inhibition of these two distinct classes of targets, COX enzymes and Rac1/Cdc42, by S-ketorolac and R-ketorolac respectively, could each contribute to anti-cancer activity." (PMID 31344967, 2019). "Moreover, CXCR4 can modulate cancer cell migration through interactions with the downstream effector Rac1." (PMID 30261690, 2018). "The observation that oncogenic RAC1 promotes resistance to ER-stress could be important for cancer treatment because, targeting oncogenic RAC1 signalling may specifically target cancer cells over wild-type cells." (PMID 29329780, 2018). "More recently, identification of point mutants in the Rho GTPases Rac1, RhoA, and Cdc42 in human tumors has finally given rise to a new paradigm, and we can now state with confidence that Rho GTPases serve as oncogenes in several human cancers." (PMID 30544828, 2018). "These examples are supportive of a requirement for Rac1 activation in multiple cancers." (PMID 30261690, 2018). "RAC1 generally plays an important role in cancer progression and metastasis." (PMID 30591011, 2018). "Like other Rho GTPases, Rac1 is involved in the acquisition of all the hallmarks of cancer." (PMID 30544910, 2018). "We do not understand how dominant-negative mutants of RhoA can cause cancers, and we do not understand why Rac1/P29S can be an oncogene when it negatively regulates adhesion-dependent cell migration and invadopodia formation." (PMID 30544828, 2018). "In early stage recurrence, the significant pathway associated genes upregulated were MMPs and genes associated with cancer cell adhesion/motility including CDC42, RAC1 while a significant upregulation of WP genes including Wnt4 and Wnt16 was noted during stage IIIc recurrence." (PMID 27902969, 2017).